SNHG3 (small nucleolar RNA host gene 3)
Diseases named in the same sentence as SNHG3 in open-access papers (continued):
Sharing a sentence is not in itself a finding about the gene and the disease.
tumor (continued). "Besides, SNHG3 affects tumorigenesis and prognosis of cancers by participating in various biological process, including promoting cell proliferation, tumor migration and invasion, cell cycle progression, inhibiting apoptosis, and drug resistance." (PMID 32802874, 2020). "Furthermore, overexpression of SNHG3 significantly promotes tumor proliferation, migration and invasion, indicating that SNHG3 is a carcinogenic lncRNA." (PMID 33292213, 2020). "In addition, we employed xenograft models with SNHG3 interference in MKN-45 cells, and found knockdown of SNHG3 significantly inhibited the growth of MKN-45 cells-derived tumor." (PMID 31534128, 2019). "In addition, we experimentally validated the critical contributions of SNHG3 in tumor metastatic processing." (PMID 31534128, 2019). "However, we need to further explore the effect of SNHG3 knockdown on tumor metastasis in vivo." (PMID 36208024, 2023). "Importantly, SNHG3/c‐MYC/BMI1 axis may be a novel target for regulating tumor growth and metastasis in BLCa patients." (PMID 36208024, 2023). "In addition, our clinical data combined with qRT‐PCR results demonstrated that the expression level of SNHG3 was significantly correlated with clinicopathological parameters, including tumor grade, muscle invasion, and TNM stage (Supplemental Sections 3.1 and 3.2)." (PMID 36208024, 2023). "In addition, IVIS imaging revealed that SNHG3 knockdown could significantly inhibit M‐NSG mice xenograft tumor growth." (PMID 36208024, 2023). "Additionally, we constructed xenograft tumor models in nude mice and confirmed that knockdown of SNHG3 could restrain PCa tumor growth and elevate methionine dependence in vivo." (PMID 35123415, 2022). "Hence, SNHG3 knockdown hindered tumor growth of PCa in vivo." (PMID 35123415, 2022). "Interestingly, SNHG3 showed promoter hypermethylation levels in tumor tissues." (PMID 36148010, 2022). "Besides, we validated the contributions of SNHG3 in tumor metastatic process." (PMID 32284745, 2020). "Our results showed that SNHG3 was overexpressed in tumor tissues of CRC patients which was consistent with previous findings 32, 33, and we also found a higher expression level of SNHG3 in serum-derived exosomes from CRC patients." (PMID 38725844, 2024). "To further examine the expression pattern of SNHG3 and β-catenin in human CRC tissues, we collected 69 specimens of frozen tissues including tumor and normal for RNA detection." (PMID 38725844, 2024). "SNHG3 was found significantly upregulated in NSCLC, contributing to tumor growth, migration, and invasion." (PMID 39349640, 2024). "The strong tumor correlation shown by RCC1/SNHG3/SNHG12, especially RCC1, in tumor diseases deserves further investigation." (PMID 36148010, 2022). "Compared with the normal group, the expressions of EP300-AS1 and TBX5-AS1 was down-regulated in the tumor group, while the expressions of LINC00857 and SNHG3 were up-regulated." (PMID 36387240, 2022). "Moreover, we manifested that SNHG3 knockdown could hinder in vivo PCa tumor growth." (PMID 35123415, 2022). "The results of qRT-PCR were suggesting that compared with the normal group, the expressions of EP300-AS1 and TBX5-AS1 were down-regulated in the tumor group, while the expressions of LINC00857 and SNHG3 were up-regulated." (PMID 36387240, 2022). "NUTM2A − AS1, NUTM2B − AS1, SNHG3, and THUMPD3 − AS1 were found to be highly expressed in tumor samples." (PMID 35615532, 2022). "The results suggest that RCC1/SNHG3/SNHG12 are involved in the immune infiltration process to some extent and play an important role in immune-tumor interactions." (PMID 36148010, 2022). "SNHG3-203, TERC-201 and SNHG12-202 were upregulated, while ENST00000610809, ENST00000443132 and ENST00000619523 were downregulated in the EMPD tumor group." (PMID 34895219, 2021). "We also found that high expression of SNHG3 was related to poor DFS and indicated higher tumor grade and more advanced tumor stage." (PMID 34336642, 2021).
tumor (continued). "As expected, western blot verified that inactivation of SNHG3 distinctly led to the elevation of phosphorylated AKT, mTOR and ERK, indicating that SNHG3-silencing triggered tumor progression in PTC by modulating AKT/mTOR/ERK signaling pathway." (PMID 32284745, 2020). "In the core ceRNA network, only 3 of 10 RNAs (SNHG3, TSNAP1 and SLC43A1) are up regulated in the tumor tissues, suggesting their potential tumor promotion effect." (PMID 32849794, 2020). "Further mechanistic analyses revealed that knockout of SNHG3 activated the AKT/mTOR/ERK pathway in PTC cell lines and the mTOR inhibitor AZD8055 abrogated the tumor-promoting effect induced by SNHG3 inhibition." (PMID 32284745, 2020). "The result of immunohistochemistry revealed that after the inhibition of SNHG3 expression, Notch1-, Notch2- and Notch3-positive cells in MCF-7 xenograft tumor increased (p < 0.05)." (PMID 32883233, 2020). "In contrast, SNHG3 and SNHG5 exhibit tumor-suppressive effects in some studies." (PMID 41234719, 2025). "Among them, SNHG3 regulates CRC development by regulating proliferation, differentiation and apoptosis, CASC21 regulates CRC development by regulating cell growth, and XIST and NEAT regulate tumor histogenesis and migration by regulating cell migration." (PMID 39830506, 2024). "Also, there have been many reports indicating that SNHG3 and SNHG12 are aberrantly expressed in many tumor tissues and can be involved in the development of a variety of tumors and diseases." (PMID 36148010, 2022). "Furthermore, overexpression of SNHG3 and SNHG12 significantly promoted tumor proliferation, migration and invasion, suggesting that they are an oncogenic lncRNA." (PMID 36148010, 2022). "We evaluated the expression of RCC1/SNHG3/SNHG12 in 33 different cancer types using several databases such as GEPIA, UALCAN, and TIMER2.0, and found that they were significantly differentially expressed in tumor tissues and normal tissues." (PMID 36148010, 2022). "Similarly, all studied SNHGs are involved in EMT through activation of various athways including Notch-1, but in vivo experiments reveal a more crucial role in tumor growth and metastasis for SNHG1, SNHG3, SNHG5, SNHG12, and SNORA71A." (PMID 36139687, 2022). "Finally, NUTM2A − AS1, NUTM2B − AS1, SNHG3, and THUMPD3 − AS1 were identified to be highly expressed in tumor samples and were negatively correlated with prognosis." (PMID 35615532, 2022). "For instance, more than 20% competitive partner genes of SNHG3 were also regulated by LINC00665, indicating that they may exhibit a similar mechanism in the tumor." (PMID 32849794, 2020). "Taken together, our findings identified a lncRNA SNHG3 that functions its tumor-suppressor role during PTC development and SNHG3 might serve as a promising candidate for target therapy of PTC." (PMID 32284745, 2020). "Mechanistically, SNHG3 knockdown in CAF-secreted exosomes suppressed glycolysis metabolism and cell proliferation by the increase of miR-330-5p and decrease of PKM expression in tumor cells." (PMID 31956955, 2020). "SNHG3 depletion has been shown to inhibit cell viability, proliferation and aggressiveness by releasing the negative regulatory effects of miR-139-5p on Topoisomerase II Alpha (TOP2A), identified as the downstream factor of miR-139-5p, and stimulating tumour progression." (PMID 33968736, 2021). "In another study, four lncRNAs (SNHG3, RMST, ZNF667-AS1,and COLCA1) were demonstrated to be significantly dysregulated according to the next-generation sequencing on a cohort containing 48 renal cell carcinoma paired tumor and non-tumor tissues, and further validated by qPCR." (PMID 41042421, 2025).
cancer (54 papers, 2018 to 2025). A tumor composed of atypical neoplastic, often pleomorphic cells that invade other tissues. "A recently discovered long non-coding RNA, SNHG3, is identified to have associations with cancer, which displays atypical expression patterns and functions as an oncogene in various cancers." (PMID 41042421, 2025). "Small nucleolar RNA host gene 3 (SNHG3) is located on chromosome 1p35 and is mainly associated with the occurrence and development of various malignant tumors." (PMID 39898106, 2025). "In vitro gain- or loss- of function experiments have shown that SNHG3 plays a crucial role in cancer cell proliferation." (PMID 41042421, 2025). "For instance, EVs released by cancer-associated fibroblasts (CAFs) containing the lncRNA SNHG3 are absorbed by BC cells, where SNHG3 acts as a sponge for miR-330-5p, thereby reprogramming cellular metabolic pathways." (PMID 39763590, 2024). "This review highlights SNHG3's substantial impact on various cancer processes and its potential as a diagnostic and therapeutic tool for aggressive cancers." (PMID 39349640, 2024). "The landscape of RCC1/SNHG3/SNHG12 associated with various immune infiltrations in human cancers was demonstrated using TIMER2.0." (PMID 36148010, 2022). "Long noncoding RNA small nucleolar RNA host gene 3 (SNHG3) has been implicated in the initiation and progression of multiple human cancers." (PMID 35030969, 2022). "RCC1/SNHG3/SNHG12 are not only highly expressed in a variety of cancers, but also are risk factors for poor prognosis." (PMID 36148010, 2022). "SNHG3 is encoded at position 1p35.3 in humans, and it has been shown to be upregulated in many cancer types suggesting a potential oncogenic role for this lncRNA." (PMID 34898477, 2021). "LncRNA small nucleolar RNA host gene 3 (SNHG3) is up‐regulated in various cancers and positively associated with poor prognosis of these cancers." (PMID 32596993, 2020). "Although the oncogene roles of SNHG3 were well recognized in a bunch of cancers, the functionality and underlying mechanisms of SNHG3 in Bca remain uncovered." (PMID 32596993, 2020). "Overexpressed SNHG3 was strongly associated with poor survival and clinical outcomes in human cancers and therefore can serve as a promising biomarker for predicting patients' prognosis." (PMID 32802874, 2020). "All subgroup analyses showed similar results that high expression of SNHG3 was significantly associated with worse OS in various cancers." (PMID 32802874, 2020). "Recent findings suggest that abnormal SNHG3 expression could be a diagnostic and prognostic factor for various cancers." (PMID 41042421, 2025). "Additionally, SNHG3 has been demonstrated to hold promise as a diagnostic biomarker and a tool for prognostic assessment in cancer patients." (PMID 41042421, 2025). "Altered expression levels of SNHG3 may serve as diagnostic markers, while targeting this lncRNA could open avenues for new treatments addressing cancer and inflammatory diseases." (PMID 39969652, 2025). "Elucidating the regulatory mechanisms would not only advance fundamental understanding of SNHG3 but also facilitate its translational applications in cancer diagnostics and targeted therapeutics." (PMID 41042421, 2025). "Recent studies have highlighted the crucial role of SNHG3 in regulating oncogenes and tumor suppressors, ultimately influencing the key characteristics of cancer cells." (PMID 41042421, 2025). "Recent evidence reveals SNHG3 plays a critical role in the occurrence and development of many malignant tumors." (PMID 41042421, 2025). "SNHG3 is shown to impact cancer cell behavior, such as proliferation, apoptosis, invasion, and angiogenesis, by influencing regulatory networks in cancer through interacting with RBPs or functioning as a ceRNA, and regulating protein levels." (PMID 41042421, 2025).
cancer (continued). "This review summarizes current knowledge about SNHG3’s expression, functional roles, molecular mechanisms, and implications for diagnosis and prognosis in human cancers." (PMID 41042421, 2025). "In general, SNHG-family lncRNAs are known to influence cancer cell growth and often operate via cytoplasmic post-transcriptional mechanisms, consistent with SNHG3’s localization and function in promoting malignancy." (PMID 40491847, 2025). "Subsequently, researchers identified abnormal SNHG3 expression in multiple malignant tumors and demonstrated its oncogenic role in certain cancers." (PMID 41234719, 2025). "In summary, this review offers a comprehensive overview of the current understanding of SNHG3 in human cancers and aims to provide new insights and perspectives to facilitate further advancements in this field of research." (PMID 41042421, 2025). "Numerous studies have found that SNHG3 is frequently overexpressed and promotes cancer progression in multiple tumors." (PMID 41042421, 2025). "This study identifies and categorizes several regulatory axes orchestrated by SNHG3 in human cancers." (PMID 39349640, 2024). "This review comprehensively elucidates SNHG3 as a pivotal regulator in cancer biology, particularly through its role as a competitive endogenous RNA (ceRNA)." (PMID 39349640, 2024). "A growing body of research supports SNHG3's pivotal role in cancer biology, indicating its potential as a prognostic biomarker and therapeutic target across various malignancies.." (PMID 39349640, 2024). "Studies were selected based on relevance to SNHG3's involvement in cancer pathogenesis and progression." (PMID 39349640, 2024). "These complementary findings highlight SNHG3's diverse regulatory roles in cancer, offering new avenues for diagnosis and therapy." (PMID 39349640, 2024). "Together, these studies provide nuanced insights into the SNHG3/miR-186 interplay across different cancers, offering potential therapeutic targets." (PMID 39349640, 2024). "This schematic diagram details the molecular mechanisms by which SNHG3 functions as a competing endogenous RNA (ceRNA) in different cancer types." (PMID 39349640, 2024). "This article provides an overview of SNHG3's aberrant expression and regulatory mechanisms in tumors, emphasizing its integral role in cancer pathogenesis through ceRNA mechanisms." (PMID 39349640, 2024). "Collectively, these studies contribute to a comprehensive understanding of SNHG3's roles in cancer biology and its potential applications in targeted therapies." (PMID 39349640, 2024). "In conclusion, this review consolidates current knowledge on SNHG3's ceRNA-mediated regulatory mechanisms in cancer, emphasizing its potential as a therapeutic target and diagnostic biomarker." (PMID 39349640, 2024). "Despite sparse comprehensive clinical research on SNHG3, its potential as a cancer biomarker remains promising." (PMID 39349640, 2024). "SNHG3 acts as a molecular sponge for microRNAs (miRNAs), thereby modulating multiple cancer-related signaling pathways and phenotypes such as proliferation, invasion, metastasis, drug resistance, and apoptosis." (PMID 39349640, 2024). "The study further emphasizes SNHG3's contributions to enhancing the proliferative, migratory, and invasive capabilities of HCC cells, underlining its broader implications in cancer biology." (PMID 39349640, 2024). "Collectively, these findings underscore SNHG3's potential as a biomarker for diagnosing and treating various cancer types." (PMID 39349640, 2024). "SNHG3 exhibits widespread dysregulation across diverse cancer types, underscoring its significance as a pivotal regulatory factor in tumorigenesis." (PMID 39349640, 2024). "The findings underscore SNHG3's pivotal role in cancer prevention, diagnosis, and treatment, laying a foundation for future research in cancer management." (PMID 39349640, 2024).
cancer (continued). "lncRNA small nucleolar RNA host gene 3 (SNHG3) has been implicated in the initiation and progression of multiple human cancers." (PMID 37143733, 2023). "SNHG3, a newly identified long non-coding RNA, has emerged as a significant player in the pathogenesis and advancement of various cancer types." (PMID 37348024, 2023). "The function of has-miR-137 and has-miR-2682 in cell proliferation was reported in the context of cancer, where SNHG3 acts as a direct sponge of miR-2682." (PMID 36412908, 2022). "High expression of RCC1/SNHG3/SNHG12 was poor in early DFS in pan-cancer and correlated with low DFS in ACC, LGG, LIHC, and PRAD." (PMID 36148010, 2022). "High expression of RCC1/SNHG3/SNHG12 in patients with a variety of cancers including ACC, KIRP, LAML, LGG, LIHC, and PRAD predicted lower overall survival and disease free survival." (PMID 36148010, 2022). "Overall, RCC1/SNHG3/SNHG12 can be used as a marker of poor prognosis in the early stages of pan-cancer." (PMID 36148010, 2022). "In the analysis RCC1/SNHG3/SNHG12 as a signature for drug-target response difference and association in pan-cancer, Topotecan, TKI258 and Paclitaxal were found which showed significant differences in different expression levels." (PMID 36148010, 2022). "At present, SNHG3 can serve as a ceRNA to exacerbate malignant progression of various cancers, but few studies have been carried out on its mechanism in PCa." (PMID 35123415, 2022). "Meanwhile, combined with the results of survival analysis, the role of RCC1/SNHG3/SNHG12 in some cancers is dominated by suppression of immune response." (PMID 36148010, 2022). "Researchers have revealed that SNHG3 can be a sponge of miRNA to modulate onset and progression of a variety of cancers." (PMID 35123415, 2022). "The lncRNAs SNHG12, SNHG3, and SPAG5-AS1 have been reported to be associated with the development of many types of cancer." (PMID 35704638, 2022). "Small nucleolar RNA host gene 3 (SNHG3) as a novel oncogenic lncRNA is theorized to have aberrant expression in varying cancers." (PMID 35123415, 2022). "SNHG3 is a key member of this family and a known regulator of the onset and progression of several cancer types." (PMID 34898477, 2021). "LncRNA SNGH3 (small nucleolar RNA host gene 3) is highly expressed in numerous forms of cancer, serving as an oncogene in cancer progression." (PMID 33859998, 2021). "Although SNHG3 has been recognized as a carcinogenic gene in a series of human cancers, the mechanism of SNHG3 in GC remains elusive." (PMID 34257656, 2021). "MIR31HG and SNHG3, both of which have been reported to play oncogenic role in other cancers, were 2.5- and 2.3-fold upregulated (P < 0.0002 and P < 0.0001), respectively." (PMID 32108138, 2020). "This review summarizes research progress on the abnormal expression, functions, molecular mechanisms and clinical significance of SNHG3 in tumorigenesis and cancer progression." (PMID 33292213, 2020). "Excavation of TCGA dataset valuated that SNHG3 was upregulated in various cancers and predicted worse OS and DFS." (PMID 32802874, 2020). "The pooled result demonstrated that high expression of SNHG3 was significantly related to poor OS in cancers (HR = 2.53, 95% CI: 1.94-3.31)." (PMID 32802874, 2020). "Small nucleolar RNA host gene (SNHG3), a newly identified lncRNA, has been found dysregulated in various cancers." (PMID 32802874, 2020). "To further validate the prognostic and clinical value of SNHG3 expression in human cancers, we investigated TCGA dataset." (PMID 32802874, 2020). "The CCK8 assays revealed that silencing of miR-330 and overexpression of PKM significantly rescued the suppression of cancer cell growth induced by the decreasing of CAF-secreted exosomal SNHG3 in MD-MBA-453 cells." (PMID 31956955, 2020). "The ceRNA is a typical regulatory pattern at post‐transcription level in cancers and SNHG3 was widely involved in the ceRNA pattern." (PMID 32248648, 2020).